ADA (adenosine deaminase)
Diseases named in the same sentence as ADA in open-access papers (continued):
Sharing a sentence is not in itself a finding about the gene and the disease.
cardiovascular diseases (6 papers, 2019 to 2023). "Since these pathologies are associated with ADA overexpression, the inhibition of its activity as well as binding to the surface proteins exhibit an attractive therapeutic potential in cardiovascular diseases." (PMID 33053898, 2020). "Particular attention has been paid to the involvement of ADA in the pathophysiology of relevant cardiovascular diseases and therapeutic potential of its pharmacological inhibition." (PMID 33053898, 2020). "Therefore, deaza derivatives of adenosine that do not inhibit ADA also deserve an attention in the preventing of cardiovascular diseases." (PMID 33053898, 2020).
neurodegenerative disease (6 papers, 2018 to 2024). A disorder of the central nervous system characterized by gradual and progressive loss of neural tissue and neurologic function. "Previous studies have suggested that ADA may play an important role in neurodegenerative diseases, linked to neuronal damage and inflammatory responses." (PMID 38601850, 2024). "Similarly, ADA and ADK have also been implicated in neurodegenerative diseases." (PMID 34635103, 2021). "Other enzymes involved in adenosine metabolism (ADA, ADK, CD39 and CD73) are also abnormally affected in AD, similar to other neurodegenerative diseases." (PMID 34635103, 2021).
adenocarcinoma (5 papers, 2014 to 2020). A common cancer characterized by the presence of malignant glandular cells. "The results of the present study provide the first evidence that increased levels of CK19 in pleural fluids are associated with adenosine deaminase activity in malignant pleural effusions from adenocarcinomas." (PMID 29854023, 2018). "ADA levels only correlated with CK19 fragments in adenocarcinomas, with high significance and good correlation (rho = 0.5145, P = 0.0036)." (PMID 29854023, 2018). "ADA levels were significantly positively correlated with CK19 fragments in adenocarcinomas (rho = 0.5145, P = 0.0036) and significantly negatively correlated with other diseases (rho = −0.9429, P = 0.0167)." (PMID 29854023, 2018). "Therefore, a need for increased adenosine in adenocarcinoma cells leads to increased ADA production." (PMID 29854023, 2018). "However, further studies are required to fully understand whether adenosine deaminase and cytokeratin 19 fragments play the same important role in epithelial differentiation in metastatic pleural fluids from adenocarcinomas." (PMID 29854023, 2018).
respiratory diseases (5 papers, 2013 to 2026). "The activity levels of adenosine deaminase (ADA) are significantly elevated in the saliva of animals with localized inflammation, gastrointestinal diseases, and respiratory system diseases." (PMID 38338017, 2024). "Serum ADA levels were significantly higher in PTB patients compared to healthy controls (SMD = 3.15, 95% CI: [2.51-3.79], p < 0.0001) and other respiratory diseases (SMD = 2.06, 95% CI: [1.38-2.74], p < 0.0001)." (PMID 42074437, 2026). "This study indicated that measurement of serum ADA level do not have enough sensitivity to assist in the diagnoses of tuberculosis patients from other respiratory diseases and not evaluated perform well enough to replace sputum smear microscopy." (PMID 24319523, 2013). "We concluded that serum ADA activity is not a useful test to differentiate tuberculosis from other respiratory diseases, And Can only be an auxiliary test particularly if the diagnosis of tuberculosis is in doubt." (PMID 24319523, 2013).
nephropathy (3 papers, 2021 to 2024). A nonspecific term referring to disease or damage of the kidneys. "We also found, using the Olink proteomic platform, that TNF-α and TMAO enhanced the secretion of additional inflammatory-and growth mediators associated with kidney disease; VEGFA, GDNF, CDCP1, OPG, uPA, AXIN1, MMP-1, MMP-10, PD-L1, HGF, Flt3L, 4E-BP1, CD40, CASP-8, ADA, TNFRSF9, TWEAK44–61." (PMID 38643262, 2024).
neurodevelopmental disorder (2 papers, 2023 to 2025). A behavioral and cognitive disorder with onset during the developmental period that involves impaired or aberrant development of intellectual, motor, or social functions. "Previous studies related to neurodevelopmental disorders have shown reduced concentrations or deficiencies of ADA and ATIC, while very few cases of elevated expression levels have been reported." (PMID 36818658, 2023).
benign tumors (1 paper, 2024). "Adenosine deaminase levels, IL-10 receptor subunit beta levels, TNF-related apoptosis-inducing ligand levels, and TNF-related activation-induced cytokine levels exhibited a causal relationship with thymic benign tumors and were risk factors." (PMID 38828408, 2024). "Adenosine deaminase levels, interleukin-10 receptor subunit beta expression, tumor necrosis factor (TNF)-related apoptosis-inducing ligand levels, and TNF-related activation-induced cytokine levels showed a causal relationship with thymic benign tumors, which are its risk factors." (PMID 38828408, 2024).
hematologic neoplasms (1 paper, 1993). "2-Chlorodeoxyadenosine (2-CDA) is an adenosine deaminase resistant analogue of deoxyadenosine which has shown clinical activity in human hematologic neoplasms." (PMID 8094002, 1993).
skeletal dysplasia (1 paper, 2025). Any Mendelian diseases that affects growth and development of the skeleton. "From the need for ADA throughout the body, ADA deficiency can also manifest with non-immune presentations, including hepatic dysfunction, sensorineural hearing loss, motor dysfunction, skeletal dysplasia, and cognitive and behavioral problems." (PMID 39859044, 2025).
ADA also shares sentences with these, for which no sentence is quoted: Granuloma (6 papers); hematologic malignancies (6); Hyponatremia (5); psoriasis (5); multiple myeloma (4); adrenoleukodystrophy (3); agammaglobulinemia (3); Bloom syndrome (3); gestational diabetes mellitus (3); Huntington disease (3); juvenile idiopathic arthritis (3); macrocytic anemia (3); typhoid fever (3); abdominal tuberculosis (2); atypical hemolytic-uremic syndrome (2); beta thalassemia (2); bronchogenic carcinoma (2); cholangiocarcinoma (2); Chylothorax (2); connective tissue diseases (2); esophageal cancer (2); Gaucher disease (2); haemophilia (2); Heart Disease (2); Hepatic failure (2); insomnia (2); leprosy (2); malignant pleural mesothelioma (2); Myelodysplasia (2); peritonitis (2).
A further 184 diseases each share a sentence with ADA in 2 papers or fewer.